CXCL5 (C-X-C motif chemokine ligand 5)
Diseases named in the same sentence as CXCL5 in open-access papers (continued):
Sharing a sentence is not in itself a finding about the gene and the disease.
COVID-19 (27 papers, 2020 to 2025). A disease caused by infection with severe acute respiratory syndrome coronavirus 2. "In the COVID-19 hospitalization signature, antibodies to CXCL5 and CXCL8 were negatively correlated with RBD IgG and age, but not with sex." (PMID 36879067, 2023). "CCL23, among the other seven proteins (IL-17C, MMP-10, FGF-19, FGF-21, FGF-23, and CXCL5), was higher in asymptomatic COVID-19 patients than in patients with symptoms." (PMID 37834869, 2023). "CXCL5 is responsible for the recruitment of neutrophils, which are the first and most abundant leukocyte that accumulates in COVID-19 infected lung tissue." (PMID 36614003, 2022). "In agreement with prior large-scale studies from patients and animal models of COVID-19, we found the hamster model of disease also has upregulated levels of IL-1β, CXCL5, and CXCL10." (PMID 36614003, 2022). "Patients with cardiovascular failure and hypotension requiring intravenous pressors showed lower IL-7 levels later in their COVID-19 trajectory, while CXCL5, IL-12, and ANGPT-1 levels were depressed early during the course of infection." (PMID 34177897, 2021). "In mild COVID-19, the cytokines weakly elevated in patients with asthma were IL-1β, IL-13, CXCL5, and LF." (PMID 34238349, 2021). "Involved cytokines seem to be different, with a more oriented IL-6, TNF, interferon and CXCL5 profile in COVID-19 and a more defined role for IL-6 and IL-10 in influenza." (PMID 34524562, 2021). "As COVID-19 patients progressed, a statistically significant dysregulation of CXCL5 was found." (PMID 38543303, 2024). "Thus, the chemokine antibody signature that distinguished healthy controls from COVID-19 convalescents (autoantibodies to CCL19, CCL22 and CXCL17) was different from the signature associated with COVID-19 severity (autoantibodies to CXCL5, CXCL8 and CCL25)." (PMID 36879067, 2023). "The 10- to 100-fold higher levels of the most potent human neutrophil-attracting chemokine, CXCL8, and the neutrophil-attracting chemokines CXCL1 and CXCL5 in the BAL fluid of COVID-19 versus influenza patients could explain the major neutrophil infiltration in the lungs." (PMID 34793331, 2022). "Through the analysis of the propensity score-matched biomarker screening cohort, we identified Flt3L, TRAIL, CXCL5, IL-12B, MCP-3, IL-24, and IL-8 as candidate biomarkers for severe progression of COVID-19 in elderly patients." (PMID 40426989, 2025). "A small subset of genes involved in neutrophil and T cell activation (CXCL5, CXCL9, CCL21) were expressed in both COVID-19(+) TV and COVID-19(-) PU groups." (PMID 37026002, 2023). "The combination of antibody values against CXCL5, CXCL8 and CCL25 at month 6 alone could correctly assign formerly hospitalized and outpatient COVID-19 convalescents with an accuracy of 77.5% (‘COVID-19 hospitalization signature’)." (PMID 36879067, 2023). "In fact, from the group comparison of COVID-19 vs. non-COVID-19, the authors identified 14 specific inflammatory proteins that can be related to SARS-CoV-2 infection, namely CXCL5, CXCL10, CXCL11, Gal-9, IL-18, IL-18R1, IFNγ, LIF-R, MCP-2, MCP-3, MERTK, MMP-1, PD-L1, and TNF." (PMID 35269564, 2022). "Our results suggested that disruption of the CXCL5 and CXCL1/2 axis may be important early components of the inflammatory dysregulation that is characteristic of severe cases of COVID-19." (PMID 34835277, 2021). "Strikingly, TNFSF11 (TRANCE) and CXCL5 showed a strong negative correlation with most of the early-stage inflammatory markers indicating an opposite trend of these markers in COVID-19 pathogenesis." (PMID 33239683, 2020). "By contrast, we detected a few cytokines (CXCL5, IL-1α/1β/13/17, LF) weakly elevated in asthma groups, which are not relevant to pathogenesis of COVID-19 as the levels of these proteins are not changed or even decreased in general COVID-19 patients." (PMID 34238349, 2021).
COVID-19 (continued). "Our dataset demonstrated downregulation of both CXCL5 and CXCL8 in COVID-19 (+) lung biopsy specimens, with these genes having the most negative Log2 fold change difference compared to COVID-19 (−) lung tissues." (PMID 38932146, 2024). "Antibodies against CXCL5, CXCL8 and CCL25 were all lower in previously hospitalized compared with outpatient COVID-19 convalescents, and this was not linked to the therapy received during hospitalization." (PMID 36879067, 2023). "Of note, CXCL5, CXCL8 and CCL25, which correspond to the chemokine antibodies representing the COVID-19 hospitalization signature, were not significantly different between mild and severe hospitalized COVID-19 convalescents in the Milan cohort." (PMID 36879067, 2023).
Arthritis (19 papers, 2013 to 2025). Inflammation of a joint. "These potentially include NO production via rhythms in Nos2 expression and rhythmic MMP3 production, both previously linked to arthritis-associated joint damage and regulation of inflammation, as well as other inflammation-associated disease effectors (Cxcl5, Ccl20, Mmp13, Rankl/Tnfsf11)." (PMID 38981514, 2024). "Our findings demonstrate that CXCL5 activates CXCR2 in nociceptor neurons to drive acute gout arthritis pain and joint inflammation." (PMID 38627393, 2024). "CXCL5-neuronal CXCR2-TRPA1 axis contributes to gouty arthritis pain, neutrophil influx and joint inflammation." (PMID 38627393, 2024). "Ten of the pathways of interest in arthritis were selected, highlighting the Ifng, Tnf, Jun, Il17a, Kdr, and Cxcl5 genes as having the most significant interaction and relevance." (PMID 36730179, 2023). "CXC motif chemokine ligand 5 (CXCL5) exerts proinflammatory effects in acute respiratory distress syndrome and arthritis." (PMID 37569554, 2023). "We measured CXCL1, CXCL5 IL-6, IL-8, IL-10, TNFα, and total IgG levels in the aliquots of set 1 and set 2 in eight arthritis patients." (PMID 34998422, 2022). "In a murine arthritis model, the neutralization of CXCL5 ameliorated joint inflammation, bone destruction and vascularization." (PMID 26367130, 2015). "In the arthritis model CXCL5 was preferentially deposited on the EnC surface by the action of the DARC, even though other CXC ligands were present at greater concentrations." (PMID 24872191, 2014). "Therefore, we unraveled the critical role of the CXCL5-neuronal CXCR2–TRPA1 axis in joint-innervating nociceptive sensory neurons to drive acute gout arthritis pain and joint inflammation." (PMID 38627393, 2024). "Functional enrichment further supported that the primed genes are heavily involved in inflammatory response, arthritis-promoting functions (Ccl2, Cxcl5, Sphk1) and, interestingly, Wnt pathway (Bmp2, Rspo3, Cd44) and stem cell differentiation (Sox5, Nrp2, Cdk6)." (PMID 35879783, 2022). "In models of collagen-induced arthritis, C. aerofaciens exacerbates the condition by increasing gut permeability and enhancing the expression of IL-17, CXCL1, and CXCL5 in intestinal epithelial cells." (PMID 40261026, 2025). "Since CXCL5 produces a significantly higher Ca2+ response than CXCL1 and makes significant contributes to gout arthritis pain, we therefore especially focused on CXCL5 in our following studies." (PMID 38627393, 2024). "Moreover, as demonstrated in animal models, the regulation of the CXCL5 and CXCR2‐TRPA1 axis contributes to nociceptive activity in arthritis." (PMID 41020650, 2025). "Based on the IPA analysis BmA pre-exposure before LPS E. coli re-stimulation affected several pathways like granulocyte and agranulocyte adhesion and diapedesis (PPBP/CXCL7, PECAM1, CCL20, CXCL5, CXCL6, MMP9), IL-17 in psoriasis, arthritis and signaling in airway cells (CCL20, CXCL5, CXCL6)." (PMID 30796272, 2019). "Moreover, improvement or resolution of arthritis in murine models has been seen after treatment with antibodies to macrophage-derived angiogenic chemokines, including IL-8, ENA-78/CXCL5, MIP-1α/CCL3, MCP-1/CCL2, and fractalkine." (PMID 23725043, 2013). "Another way that mast cells might drive arthritis was proposed to be through the release of tryptase/heparin complexes, which were shown to induce the expression of the neutrophil chemoattractants, CXCL1, CXCL5, and CXCL8, in cultured fibroblast-like synoviocytes." (PMID 27313578, 2016). "In an arthritis model, Bmal1 deletion in fibroblast‐like synoviocytes (FLS) led to increased Cxcl5 expression and neutrophil recruitment into the joints of mice; however, the molecular mechanism that links Bmal1, Cxcl5, and neutrophil recruitment was not determined." (PMID 36624683, 2023).
atherosclerosis (19 papers, 2012 to 2025). A disease characterized by the build-up of fatty material and calcium deposition in the arterial wall resulting in partial or complete occlusion of the arterial lumen. "CT-1 deficiency in advanced atherosclerosis mediated regulation of paracrine factors, such as interleukin (IL)-3, IL-6, IL-9, IL-15, IL-27, CXCL5, MCP-3, MIP-1α and MIP-1β." (PMID 32238841, 2020). "More specifically, these chemokines are widely recognized for their vital role in the recruitment of monocytes (CCL2), neutrophils (CXCL5/6), and lymphocytes (CXCL10), which have all been implicated in the pathogenesis of atherosclerosis." (PMID 39201392, 2024). "In our mouse model of atherosclerosis, CXCL5 expression increased during disease progression, but this was not linked to neutrophil infiltration." (PMID 39726810, 2024). "CXCL5 has a protective role in atherosclerosis, by directly controlling macrophage-foam cell formation." (PMID 31234556, 2019). "CXCL5 is increased in atherosclerosis, mediating a protective role in a mouse model by modulating macrophage activation." (PMID 28821884, 2017). "Serum levels of chemokine CXCL5 have also been associated with intima-media thickness of the common carotid artery, a marker of preclinical atherosclerosis, and CXCL5 levels are reduced by anti-inflammatory statin therapy." (PMID 26617980, 2015). "The aberrant expression of CXCL5 has been detected in various human diseases including atherosclerosis, inflammatory bowel disease, and cancer." (PMID 24695525, 2014). "Platelets chemokines (e.g. RANTES, PF4, SDF-1, MCP-1, CXCL5, CXCL7) and newly synthesized active cytokine-like factors [e.g. IL-1β, CD40 ligand (CD40L), β-thromboglobulin] are implicated in the development of atherosclerosis." (PMID 23372649, 2013). "Animal studies have provided results suggesting that CXCL5 may slow the progression of atherosclerosis by preventing the accumulation of macrophages and the formation of foam cells." (PMID 39028281, 2024). "Since CXCL5 is known to slow the progression of atherosclerosis, strategies that target sdLDL particles could enhance the protective effects of CXCL5, offering potential benefits for the management and treatment of atherosclerotic CVD." (PMID 39028281, 2024). "In atherosclerosis, oxidized LDL (ox-LDL) particles and other inflammatory stimuli in the arterial wall trigger the release of CXCL5, which recruits neutrophils to the endothelium." (PMID 39028281, 2024). "Mediators involved in atherosclerosis (CX3CL1/fractalkine, CCL8, M-CSF, CXCL5, CCL4, HGF), tissue remodeling (MMP-12, MMP-1, MMP-10) and angiogenesis (VEGF-A) were also increased in AD." (PMID 28821884, 2017).
colitis (19 papers, 2012 to 2025). Inflammation of the colon. "In mice with DSS colitis, colonic Cxcl5 expression was significantly higher during the light phase at ZT0 and ZT6, but not ZT12 and ZT18, and Tnfa was significantly elevated at all timepoints except ZT18." (PMID 40822350, 2025). "CXCL5 expression is characteristic of colon adenocarcinoma and colitis, but CXCL5+ cells are also occasionally found scattered in the healthy colon, indicating highly localized induction of this cytokine." (PMID 38225383, 2024). "The expression of CXCR2 and its ligands CXCL1 and CXCL5 was markedly lower in the PAI-1 KO group than in the WT (colitis) group following DSS treatment." (PMID 37151884, 2023). "Our data suggest that the involvement of PAI-1 in the pathogenesis of colitis mainly affects CXCL1/CXCL5 and their receptor CXCR2, which are important for neutrophil recruitment and tissue injury." (PMID 37151884, 2023). "Consistent with alleviated colitis in REGγ−/− mice, ELISA analysis of colonic explants revealed less production of pro-inflammatory cytokines and chemokines including KC, MIP2α, CXCL5, IL-1β, IL-6 and TNFα in REGγ−/− mice than in WT counterparts." (PMID 26899380, 2016). "Blocking CXCL5 activity using the CXCR2 antagonist SB225002 is highly effective in ameliorating acute experimental colitis and ischemic brain injury." (PMID 26738635, 2016). "Similar to our observations in human UC, there was significant upregulation of the neutrophil-active chemokines Cxcl1, Cxcl2, Cxcl3 and Cxcl5 across all models of colitis tested, indicating that this core chemokine module is conserved in colitis development across species." (PMID 36192482, 2022). "Taken together, these data support the notion that IL-22-mediated induction of neutrophil-active chemokines, including CXCL1 and CXCL5 is functionally important in the recruitment of CXCR2+ neutrophils, and that this pathway has an important pathogenic function in colitis." (PMID 36192482, 2022). "We therefore measured serum levels of sCD163 and CXCL5 at days 0 (immediately before the administration of nivolumab and IFN-β) and day 42, the earliest point at which severe irAEs (colitis, skin rash) caused by nivolumab might be expected to occur." (PMID 29050354, 2017). "CXCL5 is involved in the regulation of CXCR2-dependent neutrophil trafficking and has been associated with the pathology of inflammatory bowel disease in human and DSS-induced colitis in mice." (PMID 29057967, 2017). "The RNA array revealed that the CXC chemokines CXCL1 and CXCL5 and their common receptor CXCR2 were among the most significantly different genes between the PAI-1 KO mice with DSS-induced colitis and the WT mice." (PMID 37151884, 2023). "RT‐PCR and IHC analysis validated that TOE up‐regulated the expression of Adh5, Aldh3a2 and Acox3, but down‐regulated the expression of CCL20, CXCL5, CCR6 and CXCL1 in DSS‐induced colitis." (PMID 31565850, 2019). "In addition, DEGs associated with the immune receptor (Lrrc19), cell chemotaxis (Ccr7, Cxcl1, Cxcl5, Cxcl9, and Cxcl10), and inflammatory response (IL1r11, IL11, Tnf, IL1β, and IL18) were also upregulated in the colonic tissue of colitis mice in DVF group." (PMID 38172943, 2024). "Expression of Cxcl2 and Cxcl5, the proteins of which are known to target neutrophils and have suspected roles in IBD, was significantly increased in the DSS and TSR-treated mice during the acute phase of colitis." (PMID 22509329, 2012).
Insulin resistance (19 papers, 2009 to 2025). Increased resistance towards insulin, that is, diminished effectiveness of insulin in reducing blood glucose levels. "ENA-78/CXCL5, which is secreted by macrophages, has been linked to inflammation in adipose tissue and insulin resistance." (PMID 26197341, 2015). "Moreover, CXCR2-deficient mice are resistant to diet-induced insulin resistance and diabetes, mainly because CXCL5 blocks insulin signaling in muscle by activating the muscle Jak/STAT/SOCS pathway through the CXCR2 receptor." (PMID 32377527, 2020). "Due to the positive association of CXCL5 with insulin resistance and the important role of insulin resistance in the pathogenesis of PCOS and since this cytokine has been studied in obese people so far, we have decided to evaluation this cytokine in PCOS women with normal body mass index." (PMID 29387827, 2017). "Elevated CXCL5 levels were strongly and independently associated with insulin resistance." (PMID 22292925, 2012). "After studying the liver biopsies of NAFLD patients, it was stated that MALAT1 acts as a regulator of hepatic inflammation and fibrosis and of insulin resistance by targeting the C-X-C motif chemokine ligand 5 (CXCL5)." (PMID 41226441, 2025). "CXCL5 is able to inhibit insulin action in muscle by activating the Jak/STAT/SOC signalingpathway showing that CXCL5 can induce insulin resistance." (PMID 20157549, 2009). "However, CXCL5 in insulin-sensitive tissues, such as muscles, mediates insulin resistance through the Jak2/Stat5 signaling pathway." (PMID 40801626, 2025). "It is not known, though less likely, if the change of insulin level and insulin resistance may impact on the effects of CXCL5 inhibition on angiogenesis in the different animal models." (PMID 37420254, 2023). "CXCL5 could induce insulin resistance by inhibiting the insulin signaling pathway in muscle, adipose tissue, and macrophages." (PMID 37420254, 2023). "Furthermore, the authors showed that CXCL5 serum concentration is increased in obese patients with insulin resistance, suggesting that CXCL5 also promotes insulin resistance in humans." (PMID 23991422, 2013). "Furthermore, the involvement of CXCL5 in adipose tissue macrophage infiltration and muscle insulin resistance has already been described." (PMID 23824685, 2013). "Among pro-inflammatory chemokine, CXCL5, a chemokine ligand of CXCR2, has been related to insulin resistance and obesity-related disorders." (PMID 34571976, 2021). "Following injection of anti-CXCL5 antibody or CXCR2 antagonist as CXCL5 receptor, in obese mice improves insulin resistance and decreases fasting glucose levels." (PMID 29387827, 2017). "CXCL5 by blocking insulin signaling pathway through activating the pathway of Jak2/STAT5/SOCS2, plays an important role in the development of insulin resistance." (PMID 29387827, 2017). "Studies have shown that CXC motif chemokine ligand 5 (CXCL5) and its cognate chemokine receptor CXCR2 also support development of insulin resistance." (PMID 24741577, 2014). "In support of this view, studies have shown that several other chemokines such as CCL5, C-X-C motif chemokine ligand 5 (CXCL5) and CXCL14 are all involved in adipose macrophage infiltration and pathogenesis of insulin resistance." (PMID 23824685, 2013). "Other proteins known to be upregulated during insulin resistance by adipose tissue such as RANTES, MCP1, PLAUR, CXCL5, were found in our studies to be upregulated in both adipose- and liver tissues." (PMID 21978410, 2011).